CUBN (cubilin)
Diseases named in the same sentence as CUBN in open-access papers (continued):
Sharing a sentence is not in itself a finding about the gene and the disease.
Sepsis (2 papers, 2013 to 2022). Sepsis is defined as life-threatening organ dysfunction caused by a dysregulated host response to infection. "Cbl is likely to be, at least in part, functionally deficient in sepsis, as indexed by the down-regulation of the Cbl receptors, megalin and cubilin, in the kidneys of endotoxaemic mice, the kidney being known, as a Cbl homeostatic regulator, to reduce its Cbl uptake in states of Cbl deficiency." (PMID 23781123, 2013).
albuminuria (1 paper, 2021). The presence of albumin in the urine, an indicator of KIDNEY DISEASES. "Albuminuria in 2K-1C rats was accompanied by downregulation of the glomerular slit protein podocin, reduction of the endocytic receptors megalin and cubilin, and a marked decrease in the expression of the ClC-5 chloride channel, compared to 2K animals." (PMID 34177612, 2021).
atherosclerosis (1 paper, 2022). A disease characterized by the build-up of fatty material and calcium deposition in the arterial wall resulting in partial or complete occlusion of the arterial lumen. "Some mutated genes are related to atherosclerosis, such as FAAH, KALRN, ATP10D, CUBN, APOA5, and LRP1." (PMID 36071494, 2022).
bladder cancer (1 paper, 2024). "This study aimed to investigate the potential of the cubilin/myeloperoxidase (CUBN/MPO) ratio as a high-grade T1 bladder cancer biomarker." (PMID 38530585, 2024). "This study highlights the potential of the CUBN/MPO ratio as a prognostic biomarker for high-grade T1 bladder cancer." (PMID 38530585, 2024). "Our results suggest that low CUBN/MPO ratio could be a biomarker to select aggressive high-grade T1 bladder cancer patients to be candidates to early cystectomy and improve their oncologic outcome; however, a prospective trial will be necessary." (PMID 38530585, 2024). "However, despite these limitations, these results must be considered as a preliminary work and further work should be conducted to evaluate and validate the role of CUBN/MPO ratio and to find the biological mechanisms underlying the relationship between CUBN and MPO in high-grade T1 bladder cancer." (PMID 38530585, 2024). "In contrast, this paper investigates a specific biomarker, the CUBN/MPO ratio, in high-grade T1 bladder cancer." (PMID 38530585, 2024).
bladder tumours (1 paper, 2024). "Here, we demonstrated that the mean ratio value of CUBN/MPO was significantly lower if patients had experienced bladder tumour recurrence or progression." (PMID 38530585, 2024). "However, this is the first time a ratio between a supposed protective protein (cubilin) and a cancer aggressiveness promoter (MPO) measured in the urine of patients has been studied as a prognostic risk factor to predict recurrence and progression to muscle-invasive T1 bladder tumours." (PMID 38530585, 2024).
cervical adenocarcinoma (1 paper, 2021). An adenocarcinoma arising from the cervical epithelium. "CircSPIDR was found to sponge miR-431-5p, thereby de-repressing sortin-related VPS10 domain-containing receptor 1 (SORCS1) and cubilin (CUBN) and inhibiting the development of cervical adenocarcinoma." (PMID 34326275, 2021).
choroidal melanoma (1 paper, 2025). Malignant tumor of melanocytes of the choroid. "We examined five proteins that help cells handle nutrients and signals, Megalin, Cubilin, Caveolin-1, GIPC1, and DAB2IP, in normal eye tissue, retinoblastoma, and different forms of choroidal melanoma." (PMID 41374987, 2025).
congenital heart disease (1 paper, 2022). A heart disease that is present at birth. "In this regard, previous studies have observed a significant increase in the risk of congenital heart disease for carriers of the wild-type allele of the CUBN SNP rs11254363." (PMID 35807880, 2022).
Endotoxemia (1 paper, 2015). "Endotoxemia and acute renal injury, which are common in septic foals, decrease the expression of megalin and cubilin in rodents." (PMID 26046642, 2015).
epithelioid melanoma (1 paper, 2025). "Epithelioid melanoma also demonstrated reduced CUBN expression, characterized by weak, discontinuous fluorescence, which was limited to small epithelial clusters." (PMID 41374987, 2025). "In RB and epithelioid melanoma, CUBN expression was markedly reduced, while spindle melanoma retained expression at control-like levels." (PMID 41374987, 2025). "CUBN expression decreased in retinoblastoma and epithelioid melanoma, was retained in spindle melanoma, and increased in mixoid-cell melanoma." (PMID 41374987, 2025). "Together, these results illustrate that CUBN expression is reduced in RB and epithelioid melanoma, retained in spindle melanoma, but strikingly upregulated in mixoid melanoma, highlighting subtype-specific differences in CUBN regulation among ocular tumors." (PMID 41374987, 2025). "CUBN was reduced in RB and epithelioid melanoma and retained or increased in other subtypes." (PMID 41374987, 2025).
factor deficiency (1 paper, 2013). "Mutations in the cubilin (CUBN, OMIM # 602997) and amnionless (AMN, OMIM # 605799) genes account for most cases of IGS, whereas mutations in the gastric intrinsic factor gene (GIF, OMIM # 609342), which cause intrinsic factor deficiency (IFD), phenocopy genuine IGS." (PMID 24044590, 2013).
glomerular diseases (1 paper, 2025). "The findings emphasize the potential misdirection toward glomerular diseases of patients bearing CUBN variants and the general good prognosis associated with them." (PMID 40291921, 2025).
head and neck cancer (1 paper, 2017). A primary or metastatic malignant neoplasm affecting the head and neck. "Only one additional case of head and neck cancer (of 20 cases) stained positive for CUBN." (PMID 28052770, 2017).
Hematuria (1 paper, 2023). The presence of blood in the urine. "For the CUBN variant, both hematuria and uACR were significant in the model (p < 2.5E−6 and p < 6.61E−4, respectively)." (PMID 37872228, 2023). "For CUBN, the findings potentially expand the phenotypic spectrum which has been previously reported to include albuminuria and has a modest association with hematuria with an effect size of 1.12 (1.02–1.23; p = 0.024) and was replicated in the Geisinger MyCode cohort 10,37–39." (PMID 37872228, 2023).
holoprosencephaly (1 paper, 2006). Holoprosencephaly (HPE) is a complex brain malformation resulting from incomplete cleavage of the prosencephalon, occurring between the 18th and 28th day of gestation, and affecting both the forebrain and face, which results in neurological manifestations and facial anomalies of variable severity. "By contrast to the developmental anomalies and early lethality of the cubilin and amnionless nulls, megalin-deficient mice die perinatally and display abnormal morphogenesis of the forebrain (e.g., holoprosencephaly), lung and kidney." (PMID 16787536, 2006).
hypothyroidism (1 paper, 2019). Abnormally low levels of thyroid hormone. "We also identified a family in which the variants rs3213760 (LRP2) and rs12259370 (CUBN) were present in an individual with hypothyroidism and in no patients with MS." (PMID 30900415, 2019).
hypovitaminosis D (1 paper, 2015). "Other factors to consider in the pathogenesis of hypovitaminosis D are megalin and cubilin." (PMID 26046642, 2015).
kidney cancer (1 paper, 2025). Primary or metastatic malignant neoplasm involving the kidney. "We hypothesize that the CUBN gene has a protective function against DNA damage or is involved in DNA repair and, thus, its downregulation in kidney cancer increases the chance of an aggressive evolution of the disease." (PMID 40001939, 2025).
leprosy (1 paper, 2017). Leprosy is a chronic infectious disease affecting primarily the skin and peripheral nervous system. "Indeed, a strong host genetic contribution to leprosy susceptibility has been well established through the identification of leprosy susceptibility genes by both positional cloning (PARK2, LTA, HLA-C, MRC1) and candidate gene approaches (e.g. TLR1, TNF, CUBN and NEBL)." (PMID 28793313, 2017).
lupus nephritis (1 paper, 2023). Glomerulonephritis in the context of systemic lupus erythematosus. "The number of glomeruli presenting hypertrophic parietal epithelial cells positive for ClC-5, megalin, and cubilin were significantly higher in lupus nephritis patients than in controls." (PMID 37594671, 2023). "This study investigated the role of ClC-5, megalin, and cubilin in the parietal epithelial cells of kidney biopsies from proteinuric lupus nephritis patients and control subjects and identified phenotypical changes occurring in the pathological milieu." (PMID 37594671, 2023).
melanoma (1 paper, 2025). A malignant, usually aggressive tumor composed of atypical, neoplastic melanocytes. "Our data parallel this observation, as CUBN downregulation in RB and epithelioid melanoma may similarly reflect dedifferentiation and a more aggressive phenotype." (PMID 41374987, 2025). "In contrast, mixoid melanoma showed a marked increase in CUBN expression." (PMID 41374987, 2025). "Notably, myxoid melanomas demonstrated upregulation of CUBN, exceeding normal tissue." (PMID 41374987, 2025). "Similarly, our finding of CUBN upregulation in myxoid melanomas mirrors this pattern, suggesting that in specific tumor contexts, CUBN may be co-opted to promote growth or altered nutrient handling." (PMID 41374987, 2025).
ocular tumor (1 paper, 2025). "This evidence provides a mechanistic framework whereby CUBN loss in some ocular tumors could reflect epigenetic silencing." (PMID 41374987, 2025). "Integration with public datasets highlights CAV1 and GIPC1 as adverse survival correlates in UM and positions LRP2/CUBN/DAB2IP dysregulation as features of ocular tumor biology, nominating candidate biomarkers and mechanistic targets." (PMID 41374987, 2025). "Taken together, these findings establish that CUBN is downregulated in aggressive ocular tumor types but retained or upregulated in less aggressive or mixoid forms, suggesting a role as a marker of differentiation state and a potential mediator of tumor metabolism in ocular oncology." (PMID 41374987, 2025). "Collectively, Megalin–Cubilin endocytosis, CAV1-mediated membrane signaling, and adaptor/tumor-suppressor nodes (GIPC1, DAB2IP) define axes that may govern differentiation, metabolic supply, and invasion in ocular tumors." (PMID 41374987, 2025).
periodontal disease (1 paper, 2025). "CUBN was strongly associated with periodontal disease in the independent samples of African Americans (rs7082270, p = 3.1x10-7) and Hispanic/Latinos (rs1276710, p = 1.5x10-5), albeit the lead SNPs were rare and differed in each population." (PMID 41403351, 2025). "CUBN was strongly associated with periodontal disease in the independent samples of African Americans and Hispanic/Latinos." (PMID 41403351, 2025).
retinoblastoma (1 paper, 2025). A malignant tumor that originates in the nuclear layer of the retina. "However, in retinoblastoma (GSE208143), LRP2 was downregulated, while CUBN, CAV1, GIPC1, and DAB2IP were upregulated." (PMID 41374987, 2025).
spina bifida (1 paper, 2022). A congenital neural tube defect in which vertebrae are not fully formed. "As in the exome dataset of proband SB1A with the EFNB1 variant (rs772228172), four variants were annotated as homozygous (CUBN, COMT, PTCH1 and TRDMT1) and eight variants as heterozygous (CUBN,MTRR, and VANGL1) in the reported spina bifida-related genes." (PMID 35741713, 2022).
uveal melanoma (1 paper, 2025). A melanoma derived from melanocytes of the uveal tract. "Incorporating LRP2, CUBN, Caveolin-1, GIPC1, and DAB2IP into biomarker-driven clinical trial design could enhance risk stratification in uveal melanoma and RB and support the development of prognostic signatures that distinguish aggressive from indolent disease." (PMID 41374987, 2025). "To evaluate the prognostic relevance of LRP2, CUBN, DAB2IP, GIPC1, and CAV1 in uveal melanoma, we performed overall survival analysis using the GEPIA2 online platform." (PMID 41374987, 2025).
tumor (14 papers, 2017 to 2025). "The specificity and sensitivity of IHC staining for CUBN in cohorts of tumor tissue has provided an example of a novel diagnostic biomarker for RCC." (PMID 28052770, 2017). "We did not perform in vitro or in vivo manipulations (overexpression, knockdown, or knockout) of LRP2, CUBN, CAV1, GIPC1, or DAB2IP to establish causality between expression changes and tumor phenotypes." (PMID 41374987, 2025). "RB showed reduced CUBN expression, with only faint, patchy fluorescent signals remaining in scattered epithelial remnants or peripheral tumor zones." (PMID 41374987, 2025). "These roles motivate the evaluation of CUBN as a context-dependent determinant of nutrient handling and tumor behavior in ocular malignancies." (PMID 41374987, 2025). "Conversely, stratification of patients according to CUBN positivity showed a significant benefit for patients with CUBN-positive tumours in overall survival and RCC-specific survival." (PMID 38530585, 2024). "Low CUBN expression has been found by others in venous tumour thrombus and lung metastases, as compared to primary tumours of ccRCC." (PMID 31212796, 2019). "Cubilin protein expression was analyzsed in tumor tissue from a cohort of patients with metastatic renal cell cancer (n = 139) using immunohistochemistry." (PMID 28260162, 2017). "Specifically, LRP2 was significantly downregulated in RB compared to controls, whereas CUBN, DAB2IP, GIPC1, and CAV1 were significantly upregulated in tumor tissue." (PMID 41374987, 2025). "We have previously reported TMA-studies indicating that cubilin (CUBN) and annexin A1 (ANXA1) expressed in the tumor cells are predictive markers in mRCC patients treated with sunitinib and sorafenib." (PMID 32321460, 2020). "However, notable protein-mRNA discordances emerged for CUBN, CAV1, DAB2IP, and GIPC1, which showed transcriptional upregulation in GSE208143 despite protein-level downregulation in most tumor subtypes." (PMID 41374987, 2025). "In Pr4, we identified 10 mutations that were not present in the other primary tumour regions, of which three (in BLOC1S4, WDFY4, and CUBN) were shared with VT and all lung metastases." (PMID 31212796, 2019). "In our patient’s tumours, we did not observe low CUBN expression." (PMID 31212796, 2019).
cancer (13 papers, 2014 to 2025). A tumor composed of atypical neoplastic, often pleomorphic cells that invade other tissues. "The same study found low CUBN expression was associated with poor overall and cancer-specific survival in ccRCC patients." (PMID 31212796, 2019). "Following state-of-the-art validation of antibodies targeting CUBN, we analyzed the expression of CUBN in normal human tissues, a large variety of cancers and two RCC-specific cohorts." (PMID 28052770, 2017). "Owing to a highly RCC-specific expression profile, CUBN expression also has a potential role in clinical cancer differential diagnostics." (PMID 28052770, 2017). "Patient tissue representing various cancer types was constructed into a tissue microarray (n = 940) and immunohistochemistry used to investigate the specificity of CUBN expression in RCC as compared to other cancers." (PMID 28052770, 2017). "In addition, we found the expression of CUBN to be highly specific to RCC, suggesting a potential use of CUBN in clinical cancer differential diagnostics as a complement to other diagnostic antibodies in cases where RCC needs to be confirmed." (PMID 28052770, 2017). "The high specificity of CUBN expression in RCC also suggests a role as a new diagnostic marker in clinical cancer differential diagnostics to confirm or rule out RCC." (PMID 28052770, 2017). "A multi-cancer TMA cohort (cohort 1) was used to substantiate the RCC-specific expression of CUBN." (PMID 28052770, 2017). "Future experiments should test if the overexpression of CUBN and NSUN7 generates a radiation resistance phenotype and perhaps even a cancer resistance phenotype in cell lines and mice." (PMID 40001939, 2025). "As far as we know, the CUBN/MPO ratio has never been previously studied as a promising biomarker or prognostic factor for urinary cancer or any other type of cancer." (PMID 38530585, 2024). "In addition, CUBN expression appears highly specific for RCC compared to other types of cancer, rendering CUBN a possible clinical role in cancer differential diagnostics." (PMID 28052770, 2017).
infection (6 papers, 2014 to 2023). The state of being infected such as from the introduction of a foreign agent such as serum, vaccine, antigenic substance or organism. "Leptospires gradually colocalized with cubilin during the course of the infection." (PMID 29973159, 2018).
genetic disorders (1 paper, 2017). "In these genetic disorders, the down-expression of megalin/cubilin caused by impaired endosome–lysosome trafficking has also been shown." (PMID 28577559, 2017).
CUBN also shares sentences with these, for which no sentence is quoted: Proteinuria (3 papers); acute kidney injury (2); amyotrophic lateral sclerosis (2); Cardiovascular Disease (2); coronary artery disease (2); Methylmalonic aciduria (2); Parkinson disease (2); schizophrenia (2); adenosis (1); adrenal gland tumors (1); Alzheimer disease (1); autism (1); autism spectrum disorder (1); autosomal recessive disease (1); bipolar disorder (1); bronchiolitis (1); ciliopathies (1); cobalamin deficiency (1); dementia (1); depression (1); endometriosis (1); Fabry disease (1); HMGCL deficiency (1); Hyperglycemia (1); Leukoencephalopathy (1); liver fibrosis (1); lymph node metastasis (1); metabolic syndrome (1); Microscopic hematuria (1); mycosis (1).
A further 11 diseases each share a sentence with CUBN in 1 paper.